CCDC24 (coiled-coil domain containing 24)
Synonyms: MGC45441
Tractability: Antibody: the Human Protein Atlas places it where antibodies can reach.
Gene: Protein-coding gene on chromosome 1 (43,991,359 to 43,996,529, forward strand). Ensembl gene ENSG00000159214.
Subcellular location (Human Protein Atlas): Plasma membrane; Cytosol; Nucleoli
Gene Ontology:
Molecular function: protein binding
Genetic constraint (gnomAD): Loss-of-function variants: 34 observed, 29.13 expected, observed/expected ratio (o/e) 1.17, 90% interval 0.89 to 1.55. The upper end of that interval is the gene's LOEUF score, 1.55, which puts it in group 6 of 6, group 1 being the genes least tolerant of losing a copy. Missense variants: 426 observed, 386.33 expected, observed/expected ratio (o/e) 1.1, 90% interval 1.02 to 1.2. Synonymous variants: 175 observed, 151.78 expected, observed/expected ratio (o/e) 1.15, 90% interval 1.02 to 1.31.
Homologues: Orthologues: chimpanzee CCDC24 (98% identical), macaque CCDC24 (95% identical), rabbit CCDC24 (76% identical), pig CCDC24 (74% identical), dog CCDC24 (73% identical), guinea pig CCDC24 (68% identical), mouse Ccdc24 (64% identical), rat Ccdc24 (64% identical), zebrafish ccdc24 (27% identical).
Diseases named in the same sentence as CCDC24 in open-access papers:
CCDC24 is named in the same sentence as 4 diseases in open-access papers, as found by Europe PMC text mining. Sharing a sentence is not in itself a finding about the gene and the disease. The quoted sentences say what the papers report.
colon cancer (1 paper, 2021). "A recent study showed that the chromatin DNA component in NETs (NET-DNA) acts as a chemotactic factor to attract cancer cells by binding to CCDC24 during liver metastasis in breast and colon cancer patients." (PMID 34707103, 2021).
cancer (2 papers, 2020 to 2021). A tumor composed of atypical neoplastic, often pleomorphic cells that invade other tissues. "To date, the roles of CCDC24 and SLC35A2 have not been analyzed in cancer-related studies." (PMID 32716908, 2020).
CCDC24 also shares sentences with these, for which no sentence is quoted: infection (1 paper); tumor (1).